CD4 (CD4 molecule)
Diseases named in the same sentence as CD4 in open-access papers (continued):
Sharing a sentence is not in itself a finding about the gene and the disease.
tumor (continued). "The results from the TIMER database suggested that FPN1 was remarkably correlated not only with tumor purity but also with the infiltrating levels of different immune cells, including CD4+ T cells, CD8+ T cells, B cells, neutrophils, macrophages and dendritic cells, in LUAD and LUSC." (PMID 33714956, 2021). "In the Th17 lineage, RORC (receptor) is upregulated on the tumor infiltrating CD4+ T-cells and its ligands (CYP51A1, FDFT1, HSD17B7, LBR, TM7SF2, MSMO1, NSDHL) are also upregulated on the tumor cells, implying GBM expresses ligands that induces Th17 phenotype in tumor infiltrating helper T-cell." (PMID 34012510, 2021). "Recent work has also described populations of CD4+ T cells with cytotoxic potential (ThCTLs), which could be beneficial to anti-tumor responses." (PMID 33976164, 2021). "Moreover, combination therapy favorably modulated the tumor microenvironment by dampening immune-suppressive cells and increasing CD4 T cell infiltration together with their polarization toward Th1 phenotype." (PMID 34276686, 2021). "Tumor-reactive Th1 cells and tumor-promoting Th2 cells are two subtypes of CD4+ T helper cells." (PMID 33639614, 2021). "At least four components of the immune response are necessary for a positive result: the presence of appropriate APCs, the quality of induced CD4+ T helper cells, the control of regulatory T cells (Tregs) and the breakdown of the immunosuppressive tumor microenvironment." (PMID 34830221, 2021). "Thus, blocking of the inhibitory signal NKG2A by anti-NKG2A antibody would enhance the tumor killing of CD4 CTL." (PMID 33968044, 2021). "Thus, based on these reports and our present findings, we believe that GBM dictates the fate of tumor infiltrating CD4+ T cells by altering the DNA methylation of key genes that determine the cell’s fate." (PMID 34012510, 2021). "Moreover, the low-risk group had high tumor purity, high FPI, more mutations, more enrichment of immune-related pathways, more CD4+ T-related cells, higher expression of immune checkpoints, and easy response to immune checkpoint inhibitor immunotherapy." (PMID 34790582, 2021). "CD47 expression was positively correlated with CD8+ T cell infiltration (r=0.102, p=2.48e-02), CD4+ T cell (r=0.107, p=1.90e-02), Neutrophil (r=0.246, p=4.50e-08) and dendritic cell (r=0.162, p=3.71e-04), negatively correlated with tumor purity (r=-0.17, p=1.73e-04)." (PMID 34966389, 2021). "Indeed, although considered to be an anti-tumor factor at high concentrations, TNFα exhibits a deleterious effect due to its ability to stimulate regulatory CD4 T cells." (PMID 33498483, 2021). "Studies have shown that intratumoral CD4+ T cell infiltration can suppress tumor progression." (PMID 34204621, 2021). "In addition to their foreseeable role at the priming phase and despite the lack of MHC class II molecule expression in the vast majority of tumor cells, CD4 T cells are thought to exert effector functions through for instance IFN-γ secretion." (PMID 33332284, 2021). "To test whether the HNSCC tumor environment is capable of potentiating Treg generation through IL-21 and PD-L1, we cocultured CD4+ T cells with tumor explants from HNSCC patients with or without IL-21 and/or an anti-PD-1 neutralizing antibody." (PMID 34026621, 2021). "In addition, a higher diversity of the gut microbiome correlated with an increased tumor infiltration of activated CD4+ lymphocytes in tumor brush samples, indicating an interaction of the microbiome and the TME." (PMID 34830902, 2021). "Tumor-associated monocytic myeloid-derived suppressor cells (MDSCs) possess similar features, such as hyper-expression of ILT3 and ILT4, and can educate CD4+ Foxp3− IL-10+ regulatory T (TR) cells." (PMID 34680058, 2021). "Furthermore, EPDR1 expression was associated with tumor-infiltrating immune cells (TIICs), including NK cells, CD8 + T cells, CD4 + T cells, Macrophages cells, and so on." (PMID 33902536, 2021).
tumor (continued). "In addition, CD4+ T cells are required for the induction of B cell-mediated cellular immune responses against tumor cells." (PMID 34208855, 2021). "Additionally, IFN-γ acts on tumour cells, enhancing their recognition by CD8+ and CD4+ T-cells, thus further activating macrophages in the tumour, leading to tumour growth inhibition." (PMID 33808304, 2021). "Thus, new approaches that can augment the generation of host-reactive allogeneic CD4+ T cells are important for inducing greater endogenous antitumor immunity in tumor-bearing hosts." (PMID 34625113, 2021). "Besides, it was intriguing that the enhanced STING-dependent immune responses were associated with increased activation of CD4+ and CD8+ T cells because the study found that depletion of T lymphocytes eliminated the LAP deficiency-induced anti-tumor effects." (PMID 34956229, 2021). "Single-cell transcriptome analysis revealed the presence of five functionally distinct CD4+ TC clusters within the tumor, comprising early activated Tconv, uncommitted Teff, Th1 Teff but also immune-suppressive and tumor-promoting Treg, while other helper TC lineages were negligible." (PMID 33602930, 2021). "Furthermore, expression of Foxp3 and IL-10 was reduced in CD4+CD25+ gated cells isolated from tumor bearing mice treated with TAK-242 in comparison to vehicle-treated controls." (PMID 34771569, 2021). "In addition, cancer cells induce IL-22 production by memory CD4+T cells via IL-1β in order to promote tumor growth." (PMID 33846436, 2021). "Moreover, the frequencies of IFN-γ+ and Ki67+ cells as in tumor infiltrated CD4+ T cells were dramatically increased in mice transferring low-dose decitabine-pretreated CD4+ T cells comparing transferring control CD4+ T cells." (PMID 33791306, 2021). "This implies that GBM TME might influence the tumor infiltrating CD4+ T cells by way of extensive epigenetic reprogramming thus modulating the endogenous anti-tumor immune response." (PMID 34012510, 2021). "Using cGAS (cGAS−/−) and STING (Tmem173−/−) deficient mice, researchers confirmed that deletion of the pathway-related genes in mice caused complete loss of anti-tumor responses with no increased CD8+ or CD4+ TILs after Mn2+ administration." (PMID 34956229, 2021). "Moreover, in human tumors (esophageal SCC, NSCLC and HNSCC), CCL20 favors the recruitment of Th17 CD4+ T cells that also participate in tumor progression." (PMID 33924428, 2021). "To further explore the mechanisms of Qi-invigorating herbs acting on DLBCL TME, we conducted the analysis of the relationship between hub genes and tumor-infiltrating immune cells (B cells, CD4+ T cells, CD8+ T cells, neutrophils, macrophages, myeloid DCs, MDSCs) from the TIMER 2.0 database." (PMID 34955857, 2021). "In addition, they observed that Gal-1−/− CD4+ T cells had a lower migratory capacity toward tumor cells in vitro." (PMID 34680031, 2021). "However, if CD204+TAMs were highly expressed with a low expression of CD4+TILs, tumour recurrence was reduced after combination therapies (chemoradiation)." (PMID 35201470, 2021). "Besides Tregs, other tumor-promoting immune cells, such as IL-17-producing-CD4+ T cells (T helper 17 [Th17]) have also been reported to be a tumor-promoting immune cell type in PDAC murine models." (PMID 33961792, 2021). "Considering the results regarding the tumor immune microenvironment, p14/ARF-negative tumors seem to have an immune microenvironment less sensitive to immune checkpoint inhibitors, being associated with low PD-L1 and CD4 expression, and high CD163 percentage." (PMID 33828993, 2021). "In addition, CD4 T cell’s help is essential to generate efficient tumor-reactive effector CD8 T cells, notably during the process of epitope spreading." (PMID 34394096, 2021). "The central role of CD4+ T cells for control of PyMT tumors in Batf3–/– mice could be a bystander effect of an overall stimulatory tumor microenvironment or a de novo T cell response generated directly by tiDC2s." (PMID 34283809, 2021).
tumor (continued). "Longer peptide sequences are likely to contain both HLA class I and class II peptides and would, therefore, activate tumor-directed CD8+ and CD4+ T-cells facilitated by cross presentation of antigens in antigen-presenting cells (i.e. DC, macrophages, B-cells as well as tumor cells)." (PMID 34335558, 2021). "The resting NK cells and naïve CD4+ T cells were decreased in tumor tissues." (PMID 34867976, 2021). "However, due to the lack of adaptive immune system in nude mice, the influences of CHOP regimens on tumor-infiltrating CD4 + cells and CD8 + T cells, as well as T cell-derived cytokines were not investigated in our present work." (PMID 33653348, 2021). "Meanwhile, the results from the animal model indicated that IRE could rapidly inhibit local tumor growth by inducing the infiltration of CD4+ and CD8+ T cells, predominantly cytotoxic CD8+ T cells, accompanied by the decrease of Tregs." (PMID 33882892, 2021). "Since both KISIMA-HPV and VSV-GP-HPV contain the CD4 epitopes, the role of tumor-specific CD4+ T cells might be interesting to further investigate in the future." (PMID 34465781, 2021). "We speculate that better recognition of HLA class II by CD4+ T cells may lead to the elimination of tumor cells and the prevention of migration and invasion." (PMID 34362829, 2021). "CD4+ T helper 1 (Th1) cells help normalize tumor vessels by producing IFN-γ in the TME." (PMID 34294146, 2021). "Furthermore, the density of CD4+ GzmB+ T cells in the central region of the tumor is an independent predictor of prognosis in pMMR CRC patients and can also predict the outcome of patients after neoadjuvant chemotherapy." (PMID 34631551, 2021). "Tumor tissues of long-term survivors were rich in plasma cells (p = 0.005), CD4+ memory resting T cells (p = 0.01), and monocytes (p = 0.02), while naive (M0) macrophages and activated dendritic cells (DCs) were more abundant in tumor tissues from short-term survivors." (PMID 35223878, 2021). "In this phase I clinical trial, LDRT paired with immunotherapy promoted CD4+ T cell infiltration, induced de novo inflammation, and promoted tumor regression in an IFNγ-dependent manner, thus supporting the rationale for combining LDRT with immunotherapy in tumors with low T cell infiltration." (PMID 34975924, 2021). "CD4+ regulatory T (Treg) cells that express the transcription factor Foxp3 are an important T cell subset that are recruited to sites of inflammation and facilitate tumor progression and metastasis in most cancers." (PMID 35008369, 2021). "Increased levels of all TIL subsets, except CD4+, were associated with estrogen receptor‐negative tumors (p < 0.001) and high tumor cell proliferation by Ki67 (p < 0.001)." (PMID 34076969, 2021). "Moreover, CD8 T cell responses are most efficiently generated via coordinated CD4 T cell help, so MHC-II expressing APCs are critical for a comprehensive T cell response to tumor-associated antigens." (PMID 33816320, 2021). "However, our findings show that multiplexed imaging can discriminate tumor cells from reactive CD4+ T cells at the single-cell level, which is supported by protein expression differences, cell size measurements, and gene expression profiling." (PMID 34795254, 2021). "Even at this rudimentary stage, it was already recognised that spontaneous CD4+ T cell responses towards self-antigens could be harnessed to boost anti-tumour immunity." (PMID 32457487, 2021). "Furthermore, to examine the frequencies of tumor-infiltrating WT1-specific CD4+ T cells, intratumoral CD4+ T cells from WT1 peptide vaccine-treated mice were stimulated with WT135–52 helper peptide and their IFN-γ and TNF-α production was measured." (PMID 34355173, 2021). "Since CD4+ T cells help for recruitment, proliferation, and effector function of CD8+ T cells, we speculate that activated CD4+ T cells could promote the killing efficiency of tumor cells by CD8+ T cells in GC." (PMID 34966745, 2021).
tumor (continued). "For CD4+ TILs (Th2), we did not identify any associations regarding the intT nor strml infiltration and the tumor subtypes." (PMID 34944876, 2021). "Finally, mice transplanted with NR-FMT stool disclosed a rise in RORγT+ T helper 17 tumor-infiltrating cells and higher densities of regulatory CD4+FoxP3+ T cells and CD4+IL-17+ T cells in the spleen, indicating a compromised immune response by the host." (PMID 34360802, 2021). "For instance, VEGF acts as a chemoattractant for CD4+Foxp4+ Treg cells into the tumor." (PMID 33467713, 2021). "As tumor-specific CD4 effector T cells can also contribute to anti-tumor protective mechanisms, we further determined whether they also increased." (PMID 34733290, 2021). "Thus, CD4 + Th1 cells, CD4 + CTLs exert anti-tumor activity, whereas regulatory T cells, CD4 + TH2 cells show tumor-promoting activity." (PMID 34952631, 2021). "Although these three significant pathways might be the mechanisms of the activation of CD4+ T cells induced by the hub FRGs in GC, further studies are needed to provide conclusive evidence for the specific mechanisms in the tumor microenvironment (TME)." (PMID 34966745, 2021). "The paucity of CD8+ T cells and increased number of PD1+ CD4+ T cells might contribute to an immune‐suppressive microenvironment that supported the tumour cell colonization in the liver." (PMID 34021647, 2021). "The empirical evidence thus far suggests that the majority of the anti-tumour CD4+ response is directed against self-derived epitopes, regardless of whether Tconv or Treg cells respond." (PMID 32457487, 2021). "In addition, non-statistically significant differences were seen in the frequency of CD4+FoxP3+ T cells and CD11b+Ly6G+ cells in the tumours of pHIFU + ICI-treated subjects compared with controls 48 h after treatment." (PMID 34229458, 2021). "One study investigated the uptake efficiency of tumour‐derived small‐EVs by a panel of leukocyte subpopulations in the spleen and revealed that CD4+, CD8+, and sIgM+ lymphocytes showed uptake of small‐EVs in vitro but there was much greater uptake of small‐EVs by CD11b+ macrophages and CD11c+ DCs." (PMID 34194679, 2021). "Finally, to add insight into the complex molecular processes driving the SpatialScore, we examined potential recruitment mechanisms by identifying genes predictive of the spatial interactions between PD-1+ CD4+ T cells, tumor cells, and Tregs." (PMID 34795254, 2021). "CD4+ T cells kill cancer cells by allowing CD8 + T cell entry to tumor sites or mucosa." (PMID 34858987, 2021). "In the study, not only the number of CD4+ and CD8+ T cells significantly increased, but also the gene expression associated with type 1 T-cell recruitment and functionality enhanced when AXL is inhibited in R428-treated tumor-bearing mice." (PMID 34778071, 2021). "Notably, we showed that Alphataxin, as monotherapy, increased the number of CD4+ TILs and suppressed tumor growth, and when combined with anti-PD-1 immunotherapy, significantly suppressed or regressed tumor growth." (PMID 34900690, 2021). "The presence of the CD4+ T-reg cells (CD4+/FOXP3+) has been linked with poor prognosis in HCC and a reduced response to ICI therapy so decreases in tumour infiltration of CD4+ Treg cells may ease the immunosuppressive environment allowing immune recognition." (PMID 35936114, 2021). "Taken together, the intrinsic functionality of CD4 T cell immunity could be a key factor for restoring anti-tumor immunity and predicting outcomes in patients treated with ICIs." (PMID 34502325, 2021). "Finally, we will highlight some novel emergent aspects of anti-tumour CD4+ T cells and offer our perspective on future directions to accelerate translation of this knowledge into clinical therapies." (PMID 32457487, 2021). "IL-32 may promote CD8+ T cell IFNγ expression that enhances the antitumor activity, but at the same time induce CD4+ T cell Foxp3 expression, which could suppress tumor immune response." (PMID 34414188, 2021).
tumor (continued). "Moreover, univariate survival analysis indicated that CD4+ GzmB+ T cells infiltration levels in the central area of the tumor positively correlated with the patient’s OS and DFS." (PMID 34631551, 2021). "As reviewed elsewhere, critical features of CD4+ T helper 1 (Th1) cells in anti-tumor immunity include induction of effective antigen presentation by APCs, augmentation of CD8+ T cell responses, T cell homing to the tumor, direct and indirect tumor cell killing, and formation of memory T cells." (PMID 34290704, 2021). "Therefore, the correlation of the useful prognostic indicators verified above with six types of tumor-infiltrating immune cells (B cells, CD4+ T cells, CD8+ T cells, neutrophils, macrophages, and dendritic cells) was investigated using TIMER." (PMID 34093807, 2021). "In therapeutic pre-clinical models, vaccination with short MHC class I binding peptides hinders CTL priming and induce tolerance, whereas combination with CD40 agonist antibody infusion or DC stimulated in vitro with antigen-specific CD4+ T cell resulted in CTL-based anti-tumor immune response." (PMID 34012451, 2021). "We investigated the correlation of PIWIL4 and SUPT5H with the tumour microenvironment, and the results suggested that the high riskScore was positively related to the enrichment of resting natural killer (NK) cells and activated memory CD4 + T cells." (PMID 34876138, 2021). "However, research using Eμ-TCL1-based murine models has suggested a more complex role of CD4+ T cells with some studies showing an anti-tumor function, while others demonstrating a dispensable role." (PMID 33842331, 2021). "This therapy could effectively stimulate CD4+ T cells and showed a good safety profile of CEVs, exhibiting\ promising reduction in tumor cells and CD163+ macrophages." (PMID 34804956, 2021). "However, over time, the tumor cells evade CD4+ T cell immune surveillance by modifying their own surface antigens." (PMID 33995627, 2021). "In the early phase, the immune microenvironment mostly exerts anti-tumor effects, inhibiting tumor progression by producing cytokines and activating natural killer (NK), CD4+ and CD8+ T cells, suggesting that immunotherapy is a promising strategy to treat breast cancer." (PMID 34895326, 2021). "Finally, we used TIMER database to study the link between abundant tumor immune infiltrates (CD4+ T-cells, CD8+ T-cells, B-cell, neutrophils, macrophages, and dendritic cells) and the expression of CCR5 and TSPAN2." (PMID 33718151, 2021). "The findings of set 1 indicate that the ratio of CD8+ TNFR2+ PD-1+ TILs over CD4+ TNFR2+ FOXP3+ TILs was significantly higher in the chemotherapy-treated mice compared to the vehicle-treated mice, and was significantly associated with reduced tumor volumes." (PMID 34201054, 2021). "This fact indicates that upregulation of those genes may have a role in the relation of the CD4+ T cells, B cells and macrophages populations within the tumor." (PMID 35178045, 2021). "In turn, this study demonstrated that LDHA, a cancer stemness promoter, could impede the infiltration of anti-tumor immune cells (CD4+/CD8+ T cells) and enhance the accumulation of the pro-tumoral immune cells (MDSCs and TAMs) in TME." (PMID 34178639, 2021). "In agreement, it has been described that high doses of TA99 at early time points delays tumor growth, which is associated with increase in intratumoral CD4+ and CD8+ effectors, but it does not prevent exhaustion." (PMID 33520112, 2021). "Furthermore, we analyzed T cells in tumor-bearing mice using splenocyte preparations and found that oleandrin increased the portion of both CD4+ and CD8+ T cells in the spleen." (PMID 33762577, 2021). "CD4+ TILs are necessary to activate proliferation and memory in tumor-specific CD8+ TILs." (PMID 33726701, 2021).